MMP9 (matrix metallopeptidase 9)
Diseases named in the same sentence as MMP9 in open-access papers (continued):
Sharing a sentence is not in itself a finding about the gene and the disease.
breast carcinoma (continued). "Our findings about the high expression of MMP-9 in the specimens analyzed are in accordance with data published by Przybylowska and colleagues, who found increased levels of MMP-9 to correlate with G3 breast cancer." (PMID 19531263, 2009). "In spite of the supporting evidence in the literature, the significance of circulating MMP-9 in prognosis and progression of breast cancer disease requires further clarification." (PMID 19889214, 2009). "Similar significant differences between normal breast tissue and grade 2 breast cancer tissue concerning the mRNA levels were observed for MMP-9 (p = 0,0127), MMP-11 (p = 0,0007) and MMP-13 (p = 0,008)." (PMID 19531263, 2009). "NGAL overexpression in human breast cancer cell lines was accompanied by increased tumor growth, MMP-9 activity, angiogenesis and cell proliferation." (PMID 19889214, 2009). "MMP-9 plays a critical role in cancer progression, invasion and metastasis in several neoplastic diseases including breast cancer." (PMID 19889214, 2009). "The expression of the two gelatinases, MMP-2 and MMP-9, in breast cancer is well investigated in many studies using different methods." (PMID 19531263, 2009). "Elevated expression of MMP-2 and MMP-9 is positively correlated with HER-2 overexpression in mammary tumors." (PMID 20169097, 2009). "Not surprisingly, experimental evidence supports a critical role of MMPs, such as MMP-2 and MMP-9, in the invasion and metastasis of breast cancer." (PMID 18373849, 2008). "There is precedence for the role of IGF-1 in this regard via its effects on MMPs, such as MMP-2 and MMP-9 in MCF-7 breast cancer cells and in androgen-independent PC3 prostate cancer cells." (PMID 18598360, 2008). "In fact, both MMP-2 and MMP-9 have been extensively studied as biomakers and as well as therapeutic targets in breast cancer." (PMID 18373849, 2008). "Co-culture of macrophages with breast cancer cells results in a marked increase in tumour cell invasion, which is associated with upregulation of MMP-2 and MMP-9." (PMID 19014637, 2008). "The prognostic value of MMP-9 serum levels is currently unclear, but several studies have examined extensively the role of matrix metalloproteinases in breast cancer." (PMID 18474099, 2008). "In the present study, we demonstrated that the enhancement of invasive phenotype of breast cancer cells by PRDX6 was accompanied by upregulation of MMP-9 and Ets-1 expression and downregulation of TIMP-2 expression." (PMID 17980029, 2007). "Several MMPs have been implicated as having a role in breast cancer, including MMP-1, MMP-2, MMP-3, and MMP-9, among others." (PMID 17922906, 2007). "Conversely, experimental inhibition of PRDX6 expression decreased the invasive and potential potential of breast cancer cells, partially through regulation of uPAR, Ets-1, MMP-9, RhoC and TIMP-2 expression." (PMID 17980029, 2007). "All these results indicate that PRDX6 promotes breast cancer progression, partially through upregulation of uPAR, Ets-1, MMP-9 and RhoC expression and downregulation of TIMP-2 expression." (PMID 17980029, 2007). "Recently, one study has shown that MMP9 forms a complex with the hyaluronan receptor CD44 on the surface of breast cancer cells and activates downstream TGF-β, facilitating tumour cell survival, invasion and metastasis." (PMID 17242701, 2007). "CD44 associates with a proteolytic form of the matrix metalloproteinase-9 (MMP-9) on the surface of mouse mammary carcinoma and human melanoma cells." (PMID 17343740, 2007). "Overexpression of peroxiredoxin 6 leads to a more invasive phenotype and metastatic potential in human breast cancer, at least in part, through regulation of the levels of uPAR, Ets-1, MMP-9, RhoC and TIMP-2 expression." (PMID 17980029, 2007). "Similar to the observation shown here, secretion of an active form of MMP-9 was shown in metastatic breast cancer cells." (PMID 17343740, 2007).
breast carcinoma (continued). "The authors cultured peripheral monocytes with MDA-MB-231 breast cancer cells and noticed an increase in MMP-9 expression." (PMID 16168111, 2005). "The densitometric measures of MMP-2 and MMP-9 activity levels indicated that the average values of both gelatinase activities were significantly higher in breast cancers than in control sera (P<0.0001)." (PMID 15054465, 2004). "The statistical analyses have shown a significant increase of activity levels of both MMP-2 and MMP-9 in the sera of breast cancer patients compared with control sera." (PMID 15054465, 2004). "In this study we evaluate the prognostic value of MMP-9, by immunoperoxidase staining in a series of 210 breast cancer tissues." (PMID 11384099, 2001). "While in vivo studies using xenograft mouse models have shown that CLZ promotes apoptosis and inhibits MMP-9 in breast cancer, repolarizes macrophages, disrupts glycolysis in melanoma, and blocks Ca2+ -activated K+ channels in endometrial cancer, further research is needed." (PMID 41341097, 2026). "We therefore investigated the effects of LRP5-overexpressing osteocyte-derived CM on the expression of proteins associated with tumor progression (e.g., MMP9, Snail, cleaved caspase-3, IL-6, TGF-β1) and on breast cancer cell proliferation, migration, and invasion of tumor cells." (PMID 41596426, 2026). "In contrast to estradiol’s generally suppressive effects on MMP-9 in vascular settings, tamoxifen (and its active metabolites, e.g., 4-hydroxytamoxifen/endoxifen) can, in a subset of ER+ breast-cancer models, promote an invasive, matrix-degradative phenotype characterized by higher MMP-9 activity." (PMID 41304763, 2025). "Interestingly, our results observed a significant reduction in MMP‐9 protein level in breast cancer cells exposed to GW405833." (PMID 39980332, 2025). "The ability of rosmarinic acid to inhibit MMP-1, MMP-2, MMP-9, aldose reductase, and CDC25B activity may underlie how rosmarinic acid is able to inhibit the development of breast cancer." (PMID 40176865, 2025). "Studies have also shown that GATA binding protein 4 (GATA4) recruits histone deacetylase, resulting in reduced acetylation of the transcription factor p65, thereby inhibiting p65 binding to the MMP9 promoter, inhibiting the transcriptional activity of MMP9, and preventing breast cancer metastasis." (PMID 40665344, 2025). "Furthermore, HSP was able to induce apoptosis and prevent metastasis in 4T1 murine breast cancer cells by downregulating MMP-9 production and stopping the cell cycle at the Sub G1 phase." (PMID 40427522, 2025). "Notably, serum PAI-1 and MMP-9 levels were significantly elevated in patients with metastatic breast cancer compared to those with Stage I and II breast cancers." (PMID 40266038, 2025). "Only PAI-1 and MMP-9 levels increased in patients with early-stage breast cancer, suggesting that they may have evolved aggressively." (PMID 40266038, 2025). "In addition, TGFβ/TNFα costimulates the MMP9 promoter H3K36me2 through chromatin remodelling to activate MMP9 transcription and promote the invasion and metastasis of breast cancer." (PMID 40665344, 2025). "Furthermore, research has shown that Gefitinib inhibits VEGF and MMP-9, which stops breast cancer cells from angiogenesis and neovascularization." (PMID 41304988, 2025). "Similarly, Smad3 knockout in breast cancer models blocks TGFβ1-induced MMP9 expression, inhibiting metastasis." (PMID 40646747, 2025). "This combined therapy successfully reduced the lung metastasis rate of breast cancer patients by 84% by increasing the expression of cyt c and simultaneously reducing the expression of Bcl-2, matrix metalloproteinase-9 (MMP-9), and vascular endothelial growth factor(VEGF)." (PMID 41191140, 2025). "MMP2 (gelatinase A) and MMP9 (gelatinase B) are members of the MMPs family that have been shown to play a functional role in tumor angiogenesis, invasion, and metastasis, as well as in the carcinogenesis of breast cancer." (PMID 40735254, 2025).
breast carcinoma (continued). "In breast cancer, relatively high levels of BACH1 cause increased migration and invasion, intravasation, and in vivo metastasis by upregulating the transcriptional expression of matrix metalloproteinase 9 (MMP9) and C-X-C chemokine receptor type 4 (CXCR4)." (PMID 40710214, 2025). "Additionally, cell surface PGs (SDC1 and SDC4) and MMPs (MMP2, MMP7, MMP9, and MMP14) implicated in breast cancer progression were further included." (PMID 41228316, 2025). "We found that combination therapy lowered MMP-9, which may prevent cancer cell invasion in breast cancer." (PMID 40008130, 2025). "Furthermore, ANXA1 has been shown to facilitate tumor invasion in breast cancer through NF-κB activation and MMP-9 expression." (PMID 40332093, 2025). "Given that ANXA1 is overexpressed in melanoma cell lines and patient samples, it is plausible that NF-κB may similarly contribute to increased MMP-9 expression in melanoma, paralleling its role in breast cancer progression." (PMID 40332093, 2025). "Additionally, Ethyl gallate has been demonstrated to downregulate the mRNA expression of MMP-2 and MMP-9 of mammary cancer cells, thereby inhibiting cell invasion and proliferation." (PMID 40166460, 2025). "Myofibroblasts are important sources of MMPs in breast cancer, and tumour progression and adverse reactions are associated with strong expression of MMP-1, MMP-7, and MMP-9, as well as fibroblast-specific production of MMP-9, MMP-11, and MMP-1431." (PMID 38956273, 2024). "Furthermore, the gene knockout mechanism of MMP-2, MMP-7, and MMP-9 shown by CRISPR-Sp cas9 to improve cancer treatment at the gene level will also pave the way for future approaches in the treatment of breast cancer." (PMID 38774755, 2024). "Western blot analysis was used to examine the expression of EMT-related markers, and the results showed that when TSP50 was overexpressed in breast cancer cells, E-cadherin protein level was dramatically reduced, whereas MMP9, Slug and Snail protein levels were significantly elevated." (PMID 39030572, 2024). "GATA4’s influence extends to more than just MMP9 in breast cancer." (PMID 38653973, 2024). "Given the pivotal role of MMP-9 in breast cancer metastasis, strategies aimed at inhibiting this pathway could offer a promising approach to limit cancer progression." (PMID 39351229, 2024). "Our findings reveal that the interaction between TGF-β and TNF-α significantly amplifies MMP-9 expression in human MDA-MB-231 breast cancer cells, underscoring a complex regulatory network that extends beyond individual cytokine actions to their cooperative impact." (PMID 39351229, 2024). "Mice deficient in LCN2 or treated with an LCN2 inhibitory monoclonal antibody shown a reduction in tumor growth and metastasis, attributed to the destabilization of the LCN2/MMP-9 complex, underscoring the potential of such interventions in addressing breast cancer brain metastasis." (PMID 39188682, 2024). "Since both TGF-β and TNF-α are drivers of inflammation and cancer metastasis, and are co-expressed with MMP-9, we asked whether the co-exposure of breast cancer cells to TGF-β and TNF-α could amplify MMP-9 expression in these cells." (PMID 39351229, 2024). "Also, polyphenols extracted from Artemisia annua L. showed anticancer effects by suppressing CD44 and MMP9 in radio‐resistant MDA‐MB‐231 human breast cancer cells." (PMID 38783892, 2024). "In particular, the activation of MMP-2 and MMP-9 could enhance the potential for tumor cell metastasis in breast cancer." (PMID 38794187, 2024). "Conversely, Bmal1 contributes to breast cancer progression by elevating MMP9 expression." (PMID 37923872, 2024).
breast carcinoma (continued). "Targeting MMP9 can reduce breast cancer progression and modulate EMT genes." (PMID 38673967, 2024). "Consistently, Q decreased the protein levels of MMP-2 and MMP-9 in breast cancer cell lines." (PMID 39474040, 2024). "Moreover, LOX, MMP-2, and MMP-9 are more highly expressed in breast cancer tissues with axillary lymph node metastasis, suggesting a potential synergistic role in breast cancer metastasis." (PMID 39247609, 2024). "We therefore hypothesised that reducing extracellular matrix remodelling in the pulmonary vascular endothelium by reducing MMP-9 production may also be one of the mechanisms of action of RSR in inhibiting breast cancer lung metastasis." (PMID 39156102, 2024). "In breast cancer, MMP-9 acts as the prognostic marker for breast cancer progression." (PMID 38589471, 2024). "Clinical studies have further corroborated this interaction, suggesting that LCN2 could serve as a predictive biomarker for MMP-9 levels and the progression of breast cancer." (PMID 39188682, 2024). "Additionally, miR-509 suppressed the trans-endothelial migration of breast cancer cells and contributed to the suppression of MMP9 via modulation of RhoC." (PMID 39175471, 2024). "Resveratrol treatment has been found to influence similar processes when administered with gold nanoparticles in breast cancer cells: treatment (10 μM) inhibited MMP-9 at the mRNA and protein levels and reduced its activity by downregulating the NF-κB, PI3 K/Akt, and MAPK/ERK pathways." (PMID 39335164, 2024). "In conclusion, our findings support a cooperativity model in which TGF-β could amplify the TNF-α-mediated MMP-9 production via chromatin remodeling and facilitate breast cancer invasion and metastasis." (PMID 39351229, 2024). "Additionally, naringenin inhibited the growth potential of MDA-MB-231 breast cancer cells and downregulated the MMP-2 and MMP-9 expression by binding to Integrin β3, thereby blocking breast cancer cell movement and invasion." (PMID 39572023, 2024). "In breast cancer exosomes, fibronectin is involved in promoting metastasis via EMT and production of pro-inflammatory cytokines and MMP-9, metastasis-associated protein 1 (MTA1) is linked to enhanced metastatic potential and unfavourable prognosis in breast cancer patients." (PMID 38200509, 2024). "Therefore, MMP9 can be used as a biomarker in breast cancer and, ultimately, development of novel treatment options." (PMID 37180727, 2023). "Interestingly, on the contrary, BMAL1 overexpression promotes invasion and metastasis of breast cancer cells by upregulation matrix metalloproteinase 9 (MMP9), a mediator of local tumor invasion and distant metastasis." (PMID 38189049, 2023). "Concerning the link between endocan and MMP-9, it has been shown that endocan knockdown reversed MMP-9 increased expression in radiotherapy-resistant breast cancer cells; on the contrary, MMP-9 and also VEGF-A expression was significantly improved in mice overexpressing endocan." (PMID 37238720, 2023). "Wogonin exerts its anticancer effects in breast cancer may through targeting 5-LO/BLT2/ERK/IL-8/MMP-9 signaling cascade." (PMID 37560476, 2023). "Histamine has also been implicated in the modification of the invasive phenotype in MDA-MB-231 breast cancer cells by decreasing cell adhesion and altering the balance between matrix metalloproteinase 9 (MMP-9) and tissue inhibitor of metalloproteinase 2 (TIMP-2)." (PMID 37242458, 2023). "Studies have shown that CAF-derived MMP-1 and MMP-9 promote the invasion of breast cancer cells." (PMID 37496657, 2023). "In addition to having angiogenic activity, CCL2, CXCL2, and MMP-9 can also act as chemokines to recruit tumor cells, myeloid-derived cells, and macrophages, providing conditions for breast cancer metastasis while promoting further deterioration of the tumor." (PMID 38003338, 2023).
breast carcinoma (continued). "Our analysis showed that only AKT1 and MMP9 were significantly upregulated in breast cancer tissues compared to normal tissues, suggesting that they may be the most promising targets for follow-up research." (PMID 37165049, 2023). "There was an inverse correlation between the expression of MMP-2 and MMP-9 in breast cancer." (PMID 37798646, 2023). "This is consistent with earlier findings that O. indicum leaf and fruit extracts exhibit an anticancer effect on MCF-7 breast cancer cells by inhibiting colony formation and cell migration, reducing MMP-9 and ICAMP1 gene expression, and MMP-9 protein expression." (PMID 37455847, 2023). "Furthermore, it is found that poor prognosis in breast cancer is highly correlated to MMP-9 expression level." (PMID 37569509, 2023). "Adipocyte progenitors (CD45-CD34+) in xenograft and breast cancer models secrete granulocyte-macrophage colony-stimulating factor (GM-CSF) and matrix metalloproteinase 9 (MMP-9), thereby inducing immunosuppression, intratumor vascularization, as well as local and metastatic tumor growth." (PMID 36670988, 2023). "MMP-9 promotes the cell invasion property of breast cancer cells." (PMID 36986499, 2023). "Mechanistic evidence for regulation of MMP-9 expression by ADAM8-driven signal transduction in breast cancer cells is presented, lending weight to the idea that metalloproteases can mutually regulate one another in cross-talks collectively referred to as the “protease web”." (PMID 36910158, 2023). "An increase in MMP-9 enhances the metastatic potential of pan-breast cancers." (PMID 37372062, 2023). "Indeed, the overexpression of C/EBP ζ in MDA-MB-231 cells resulted in decreased MMP9 and Lcn-2 expression, coinciding with the inhibition of the migration and invasion of breast cancer." (PMID 37958332, 2023). "The data shows that in breast cancer cells, microRNA-204-5p is a direct regulator of MMP-9." (PMID 37372062, 2023). "This may be connected with the metastatic process of breast cancer (activating matrix metalloproteinase 9 (MMP9) and matrix metalloproteinase 14 (MMP14))." (PMID 37108392, 2023). "Notably, the overexpression of MMP-9 in breast cancer cell lines by CAFs substantially amplifies tumor invasiveness, primarily by activating the TGF-β/SMAD signaling pathway." (PMID 38273859, 2023). "Additionally, inflammasome pathway and IL-1β production can also be elicited by ATP or TNF-α through the P2Y2 receptor (P2Y2R) in breast cancer cells, which promotes the expression of matrix metallopeptidase-9 (MMP-9) and resultant invasion." (PMID 36932407, 2023). "However, deposition of this protein in tumor stroma has been observed in breast cancer with a more invasive phenotype, partly due to upregulation of MMP-9 and genes protecting cancer cells from endoplasmic reticulum stress." (PMID 36765749, 2023). "Additionally, glycation has been linked to activating the RAGE/TLR4/MyD88 signaling pathway and upregulating MMP9 expression in breast cancer, thus increasing migration and invasion." (PMID 37174618, 2023). "Moreover, there is an interconnection between TGF-β activation and MMP-9 expression, as an overexpression of MMP-9 increases the malignancy of breast cancer cell lines, largely via the activation of the SMADs signaling pathway." (PMID 37480151, 2023). "Furthermore, this study has provided molecular evidence for increased beta-catenin accumulation and MMP-9 expression in breast cancer cells upon exposure to adipocyte secretions collected from in vitro-derived obese adipocytes." (PMID 38068928, 2023). "A previous study also proved that the overexpression of MMP9 might contribute to increasing breast cancer cell line malignancy through modulation of the transforming growth factor-beta/SMAD signaling pathway." (PMID 36793711, 2023).